INS (insulin)
Diseases named in the same sentence as INS in open-access papers (continued):
Sharing a sentence is not in itself a finding about the gene and the disease.
Insulin resistance (continued). "As is typical for this model, plasma insulin levels rose strongly in response to HFD indicative of insulin resistance, while they increased only slightly over time on chow." (PMID 35216439, 2022). "During an insulin clamp, impaired capillary insulin delivery in humans with prediabetes and mouse models of insulin resistance results in increased insulin concentration gradient from plasma to the interstitial fluid." (PMID 35055038, 2022). "Catecholamine promotes increased insulin resistance, compromises insulin secretion, and decreases glucose uptake." (PMID 35355563, 2022). "In detail, the level of insulin secreted by pancreatic β cells is unable to keep up with the increasing insulin resistance." (PMID 36246890, 2022). "Increased obesity and excess adipose tissue provide a feed-forward mechanism that worsens insulin resistance and subsequently further increases insulin secretion from the pancreatic beta cells." (PMID 36117808, 2022). "In fact, several studies used the protein expressions of IRS-1 and GLUT4 to determine the insulin signalling related to insulin resistance." (PMID 36235772, 2022). "Here, we set the focus on a subset of the data which contains proteomics samples of individuals featuring insulin sensitivity (IS) or insulin resistance (IR), and addressed the differences between proteomic trajectories of these two groups throughout time." (PMID 35839259, 2022). "Insulin resistance is a hallmark of T2DM, defined by a decrease of insulin sensitivity in insulin-targeted tissues including the liver, skeletal muscle and adipose tissue." (PMID 36352450, 2022). "Change in glycated haemoglobin (HbA1c), fasting plasma insulin and insulin resistance (Homeostatic Model Assessment of Insulin Resistance-HOMA-IR)." (PMID 36581990, 2022). "Studies have shown that administration of FGF21 in a diabetic model reduces insulin resistance and reduces hyperglycemia by increasing the expression of transcription factors that stimulate the insulin gene." (PMID 36109786, 2022). "It has been shown that overcoming insulin resistance via intensive insulin therapy has a protective effect for the neuromuscular function in critically ill patients." (PMID 35922829, 2022). "Elevated glucose levels stimulate the pancreas to release insulin, and the tissues and cells developing insulin resistance stimulate the pancreatic β cells to produce more insulin, thereby impairing their function." (PMID 35457182, 2022). "EEI reverses insulin resistance by decreasing insulin and glucose levels, HOMA-IR index, and improving impaired glucose tolerance." (PMID 36432581, 2022). "The scientific literature defines GDM as a state of hyperglycemia developing in pregnancy as a result of insulin resistance or reduced insulin production, which resolve following delivery." (PMID 35457182, 2022). "Metabolically, DSS led to the development of a marked insulin resistance, as shown by the increased glucose, insulin plasma concentrations (and insulin resistance index) in DSS group vs. control (P < 0.05)." (PMID 36245508, 2022). "Our study showed that the late-phase insulin levels decreased after ELX/TEZ/IVA therapy initiation—an effect we interpret as insulin-resistance-improvement: less insulin is needed for lower glucose levels, and the initial insulin secretion is sufficient." (PMID 35529332, 2022). "Consistent with the insulin resistance phenotype, basal insulin levels were significantly upregulated in LKO mice fed HFD, compared with controls fed the same diet." (PMID 35349482, 2022). "We also found evidence of insulin resistance through a glucose tolerance test and by directly measuring insulin signaling." (PMID 36548717, 2022). "O-GlcNAcylation is considered to be critical in the dysregulation of the insulin signaling cascade and the molecular mechanism of insulin resistance." (PMID 35681484, 2022).
Insulin resistance (continued). "Collectively, our results identify miR-34a as a new inhibitor of insulin signaling in adipocytes, providing a potential pathway to target to fight insulin resistance." (PMID 36010657, 2022). "AD patients have lower levels of insulin in the CSF and higher plasma insulin when compared to healthy controls, indicating peripheral insulin resistance in AD patients." (PMID 36429060, 2022). "AGEs induce insulin resistance by interfering with the insulin signaling pathways through the RAGE-dependent induction of pro-inflammatory cytokines and reactive oxygen species (ROS)." (PMID 36432614, 2022). "Several insulin-sensitive tissues regulate glucose homeostasis, and compensation for insulin resistance can occur through multiple mechanisms." (PMID 34801552, 2022). "In general, insulin resistance is considered to be a decrease in the sensitivity or responsiveness to insulin metabolism including insulin-mediated glucose disposal." (PMID 36176638, 2022). "In the early stages of insulin resistance, β-cells compensate by secreting more insulin and increasing β-cell proliferation." (PMID 35574038, 2022). "LBP significantly improved the levels of insulin secretion and sensitivity, as well as alleviated insulin resistance in diabetic mice." (PMID 35845787, 2022). "While insulin sensitivity is restored at the end of puberty in normal-weight youth, insulin resistance persists in obese adolescents." (PMID 36107617, 2022). "Insulin indices including homeostasis model assessment of insulin resistance and quantitative insulin sensitivity check index were calculated to evaluate insulin resistance (IR)." (PMID 36714591, 2022). "Despite all the abnormalities that occur in stage 1, the pancreatic beta cells are still able to compensate for insulin resistance by producing more insulin (hyperinsulinemia)." (PMID 36160451, 2022). "In summary, MSC-Exos can alleviate insulin resistance in insulin-sensitive tissues, such as the liver, muscle, and fat, and restore the function of β-cells." (PMID 36339446, 2022). "The expression of adiponectin in adipose tissue can also be induced by thiazolidinediones, a family of molecules used in treatments against insulin resistance and type II diabetes such as rosiglitazone, a PPARγ agonist known for its insulin-sensitizing role." (PMID 36078135, 2022). "Insulin resistance necessitates more insulin to maintain blood glucose; therefore, not only the number of pancreatic beta cells but also insulin production per cell must be increased to compensate for this deficit." (PMID 35229479, 2022). "Insulin resistance is defined as a diminished biological response to insulin, a peptide hormone that regulates the anabolic response to nutrient availability by binding to receptors anchored in the plasma membrane of target cells in peripheral tissues." (PMID 36008933, 2022). "In fact, both fasting and postprandial glucose and insulin concentrations were significantly ameliorated, while insulin resistance was significantly decreased." (PMID 36430066, 2022). "Since DM is mainly associated with insulin resistance and decreased insulin sensitivity due to impaired insulin signal transduction, current efforts are focused on potential substances to ameliorate oxidative stress and insulin resistance." (PMID 36012897, 2022). "Amelioration of insulin resistance with insulin sensitizers is concomitant with the reduction in inflammation in insulin-resistant subjects with morbid obesity and type 2 diabetes." (PMID 35700043, 2022). "When insulin acts efficiently, oxygen consumption is thought to increase and oxygen consumption is known to be depressed in insulin resistance." (PMID 35883894, 2022). "Following obesity and insulin resistance, insulin concentrations increase by reducing the clearance rate." (PMID 36585722, 2022). "Insulin resistance should be reduced using an insulin sensitizer, so as to improve the prognosis of these patients." (PMID 36246713, 2022).
Insulin resistance (continued). "The possible mechanisms by which an inflammatory state lead to T2DM are a disturbance in insulin signaling in the liver by inflammatory molecules such as IL-6, a proinflammatory effect on insulin, or insulin resistance." (PMID 36359216, 2022). "In contrast, T2DM results from both genetic and environmental factors, and is characterised by systemic insulin resistance, hyperglycaemia, hyperlipidaemia and abnormal secretion of insulin." (PMID 36144236, 2022). "Disturbances in insulin sensitivity and induction of insulin resistance are among the molecular mechanisms through which TCF7L2 rs7903146 variant increases the risk of T2DM." (PMID 35585604, 2022). "Even though all pregnant women have some degree of insulin resistance (IR), among women with diabetes, maternal adaptation in insulin sensitivity increases oxidative stress levels." (PMID 35329371, 2022). "The fasting insulin level and homeostasis model assessment of insulin resistance (HOMA-IR) index were also elevated in HFD-ADI mice compared with HFD-CON mice (P = 0.0058 and P = 0.0075, respectively)." (PMID 35670534, 2022). "CNS insulin resistance, as discussed further below, can include low levels of CNS insulin as well as resistance at the receptor level and therefore would be better described as a deficiency in CNS insulin action." (PMID 35884888, 2022). "Fasting insulin concentrations and basal insulin resistance (HOMA-IR index) were significantly reduced after the MedDiet intervention (p = 0.001)." (PMID 36430066, 2022). "To examine insulin resistance and impairment in glucose metabolism, we evaluated the fasting blood glucose level and serum insulin level and calculated the HOMA-IR ratio in experimental animals." (PMID 35707380, 2022). "Skeletal muscle is the key tissue responsible for insulin-stimulated glucose disposal and is the major site of peripheral insulin resistance." (PMID 35147511, 2022). "Insulin resistance (IR) is a state of decreased cellular sensitivity to insulin despite an elevated or normal serum insulin concentration, which is an expression of their dysfunction." (PMID 35885586, 2022). "The intrahepatic accumulation of fatty acids and lipotoxic intermediates interferes with intracellular signaling pathways like insulin signaling, and can induce endoplasmic reticulum stress; both can contribute to the development of insulin resistance." (PMID 36140169, 2022). "We also compared fasting glucose, fasting insulin, and homeostasis model assessment for insulin resistance (HOMA-IR) scores at 24 weeks." (PMID 36699605, 2022). "Whereas Kupffer cells, similar to resident macrophages of white adipose tissue, probably contribute to maintaining insulin sensitivity of the organ system, the newly recruited macrophages rather contribute to the development of insulin resistance." (PMID 35955975, 2022). "In patients with PCOS, SHBG concentrations are usually low because of elevated androgen levels, and hyperandrogenemia promotes compensatory hyperinsulinemia and insulin resistance by increasing lipoprotein and reducing insulin clearance." (PMID 35615684, 2022). "To achieve this goal, we investigated the effect of local in vivo shRNA-mediated gene silencing of CerS1 and CerS5 on the bioactive lipid accumulation and insulin signaling pathway in gastrocnemius muscle of mice with diet-induced insulin resistance." (PMID 35053322, 2022). "The causal relationship between IFN-α and insulin resistance was elucidated in healthy individuals treated with natural human leukocytes IFN-α by impairing glucose tolerance and insulin sensitivity." (PMID 36552805, 2022). "Skeletal muscle insulin resistance, which is defined as less sensitivity of skeletal muscle to normal insulin concentration, aggravates the development of T2DM." (PMID 36368953, 2022).
Insulin resistance (continued). "In NASH progression, TNF-α induces the activation of JNK, leading to the Ser site on the IRS protein in the phosphorylated insulin signaling pathway and consequently resulting in insulin resistance." (PMID 35811658, 2022). "The aqueous extract of Syzygium paniculatum fruits alleviated hepatic insulin resistance at a 100 mg/kg dose by reducing the blockage of the insulin signaling pathway via the improvement of insulin receptor (IR and IRS-1) function in HFD-induced diabetic rats." (PMID 35684249, 2022). "Both plasma insulin and C-peptide concentrations are often elevated in people with T2DM, demonstrating underlying insulin resistance." (PMID 36204023, 2022). "The current investigation aimed to examine the differences in fat-free mass /lean body mass according to the presence of insulin sensitivity/insulin resistance/glucose tolerance/metabolic syndrome in children." (PMID 35065638, 2022). "In recent years, various inositol derivatives, which have a key role in the insulin signaling pathway as second messengers, have become a common medication for treating insulin resistance." (PMID 35888726, 2022). "Insulin resistance refers to a weak biological response to certain level of serum insulin, leading to the requirement of more insulin dosage to achieve the same effect." (PMID 35928900, 2022). "During obesity, the altered adipose tissue microenvironment induces macrophage polarization to a pro-inflammatory M1 phenotype and release of inflammatory cytokines, impairing insulin signaling and promoting the progression of insulin resistance." (PMID 36012516, 2022). "It is a result of impaired insulin secretion or insulin resistance and is characterized by hyperglycemia." (PMID 36381191, 2022). "Compared to the controls, PCOS rats showed statistically significant higher serum fasting glucose and insulin levels, as well as a higher Homeostatic model assessment index of insulin resistance (HOMA-IR)." (PMID 35845946, 2022). "Overall, the present study supports a protective role/preventive role derived from DPIN consumption on the endocrine pancreas, by reducing the load of insulin secretion and thus reducing one of the main factors contributing to insulin resistance." (PMID 36235746, 2022). "T2DM is a very common form of DM characterized by high glucose level accompanied by insulin resistance and impairment in insulin secretion." (PMID 36139069, 2022). "As a result of these processes, insulin resistance was reduced, and tissue sensitivity to insulin increased." (PMID 35885378, 2022). "JNK activation leads to phosphorylation of IRS-1ser; this disrupts insulin signaling, leading to insulin resistance, and ultimately contributing to the pathogenesis of T2D." (PMID 36145191, 2022). "Reactive oxygen species (ROS) production and the secretion of inflammatory cytokines like TNFα and C-C motif chemokine ligand 2 are elevated under conditions of excess nutrition, which eventually impairs insulin signaling and results in insulin resistance." (PMID 36207302, 2022). "To observe the effects of MLN4924 on insulin resistance, we performed glucose and insulin tolerance tests in the HFD-induced mice." (PMID 36432651, 2022). "Expression level of adiponectin, a marker for insulin sensitivity, was significantly reduced, suggesting insulin-resistance." (PMID 35102236, 2022). "In general, obese individuals with insulin resistance exhibit high levels of adipose tissue inflammation, whereas adipose tissue in insulin-sensitive obese individuals exhibits limited inflammatory properties." (PMID 36012516, 2022). "Further work from this group showed that insulin-resistant skeletal myoblasts, differentiated from hiPSC from patents with a monogenic form of insulin resistance, showed impaired insulin signalling and aberrant glucose uptake and glycogen synthesis." (PMID 36144236, 2022).
Insulin resistance (continued). "Insulin resistance defines an impairment in the biologic response to insulin stimulation of target tissues, primarily the liver, muscle, adipose tissue, and brain." (PMID 35204710, 2022). "In dyslipidemia, change in lipid levels leads to insulin resistance and reduced efficiency of insulin leading to hyperglycemia and increased fat accumulation in the liver (as observed in our study findings)." (PMID 35759880, 2022). "Sphingomyelin accumulation has been related to type 2 diabetes and observed in mouse models of insulin resistance as well as in the skeletal muscle of obese, insulin-resistant humans." (PMID 35573781, 2022). "The results showed that MOLP had inhibitory activity against α-glucosidase, alleviated oxidative stress in high glucose-induced insulin-resistant HepG2 cells, and attenuated the continued development of insulin resistance." (PMID 36293262, 2022). "As the major insulin-sensitive tissues, skeletal muscle was proved to be regulated by adipose-derived exosomes with their cargo during the development of insulin resistance." (PMID 36293266, 2022). "Insulin resistance is defined as poor sensitivity of insulin target tissues to insulin, which results in lower uptake and utilization of glucose." (PMID 36532435, 2022). "Since thiazolidinediones are also known as insulin-sensitizing agents used in the treatment of type 2 diabetes as effective agents for attenuating insulin resistance, compounds can be tested for their anti-inflammatory and antidiabetic activities." (PMID 35864866, 2022). "Results from this corroborated with previous findings in that LETZ-induced PCOS in mice resulted in higher insulin and fasting blood glucose levels, demonstrating insulin resistance and hyperglycemia, two key characteristics of metabolic diseases (MD’S)." (PMID 36518462, 2022). "Insulin resistance, which is a distinctive hallmark of T2DM, describes the failure of cells to respond to insulin during disease progression." (PMID 36045953, 2022). "Insulin resistance onset in skeletal muscle is characterized by the impairment of insulin signaling, which reduces the internalization of glucose, known as glucose uptake, into the cell." (PMID 36552772, 2022). "Decreased insulin-stimulated glucose uptake, or insulin resistance, one of the common hallmarks of type 2 diabetes, was also reported in IUGR young adults whose birth weights were below the 10th percentile for their gestational age." (PMID 35432208, 2022). "SP can inhibit glucose-induced insulin release and reduce glucose uptake, and thus improve insulin resistance." (PMID 34757591, 2022). "The increase in insulin secretion was driven by change in insulin resistance to maintain glucose homeostasis, but in some participants, insulin secretion decreased despite the increase in insulin resistance." (PMID 36012589, 2022). "With the occurrence of insulin resistance, ever higher levels of insulin are needed to maintain euglycemia until the limits of the system are reached, resulting in hyperglycemia." (PMID 35884888, 2022). "Obesity-related insulin resistance is a highly prevalent and growing health concern, which places stress on the pancreatic islets of Langerhans by increasing insulin secretion to lower blood glucose levels." (PMID 36077188, 2022). "A high-fat diet disrupts insulin signaling by affecting glucose and lipid homeostasis, which changes the regular functioning of insulin signaling molecules and results in insulin resistance." (PMID 36235831, 2022). "The prevailing ways to measure CNS insulin resistance are to measure CSF to serum insulin levels and post-mortem tissue analysis of phosphorylation events in response to insulin stimulation or total protein levels." (PMID 35884888, 2022). "The transgenic mice with GPx1 deficiency or overexpression showed additional regulatory functions of GPx1 in reactive oxygen and nitrogen species and insulin secretion and insulin resistance." (PMID 35624786, 2022).